ALK (ALK receptor tyrosine kinase)
Diseases named in the same sentence as ALK in open-access papers (continued):
Sharing a sentence is not in itself a finding about the gene and the disease.
cancer (continued). "This phenomenon of a ‘buffer’ transcript could be relevant given the vital importance of ALK activity in many cancer types." (PMID 29143801, 2017). "Within the list of top differentially expressed genes, in the UCHL1 KDs we found downregulation of the Wnt targets POSTN, SP7, and DLL1, of the transporter ABCA4, of the homeobox gene DLX4, and of genes recently linked to cancer progression ACTA2, AQ4, GRAP2, and ALK." (PMID 28472177, 2017). "NPM1 was first associated with cancer where approximately one-third of anaplastic large-cell non-Hodgkin’s lymphomas were found to express a fusion between NPM1 and the catalytic domain of anaplastic lymphoma receptor tyrosine kinase (ALK)." (PMID 27553022, 2016). "Various forms of oncogenic ALK proteins have been identified in various types of human cancers." (PMID 27641368, 2016). "Subsequently, another cancer driver was discovered, a gene rearrangement on chromosome 2, leading to the fusion gene between echinoderm microtubule associated protein like 4 (EML4) and anaplastic lymphoma kinase (ALK)." (PMID 27495736, 2016). "CHD9, a cancer driver gene, was the most significantly altered (4.0% of cases) after ALK." (PMID 27009842, 2016). "For patients living with cancer as a chronic disease, quality of life is extremely important, thus clinicians following these patients should be aware of this potential effect and more knowledge is required concerning ALK inhibition in this patient group." (PMID 25955180, 2015). "Furthermore, information on testosterone levels in patients taking ALK inhibitors targeting other alterations in cancer, for example MET and ROS, should also be gathered." (PMID 25955180, 2015). "ALK has emerged as a novel tumorigenic factor in several epithelial human cancers." (PMID 26312204, 2015). "This might explain why ALK targeted inhibitors have shown impressive clinical efficacy in ALK-rearranged malignancies, whereas in cancer patients expressing full-length ALK kinase clinical response remains unsatisfactory." (PMID 26147305, 2015). "crizotinib is a tyrosine kinaseinhibitor, anti‐cancer drug targeting ALK and ROS1." (PMID 26650444, 2015). "We think that our data suggest that novel small molecule ALK inhibitors combined with RNA interfering-based nanoliposomes could ultimately subdue many ALK-driven cancers into manageable diseases." (PMID 26299615, 2015). "Consequently, ALK-dependent tumors are extremely sensitive to ALK inhibition: indeed, the recent introduction of crizotinib has been a major breakthrough in the management of ALK-positive cancer." (PMID 25749034, 2015). "Until now, several fusion partners of ALK have been reported in various cancers." (PMID 26295973, 2015). "Crizotinib, a c-MET/ALK inhibitor, has exhibited antitumor efficacy in different types of cancers." (PMID 25193856, 2014). "Importantly, ALKF1174L also arises secondarily as a mechanism of resistance after an initial response to crizotinib in patients with ALK-rearranged cancers." (PMID 25228590, 2014). "Crizotinib demonstrates impressive initial antitumor activity in ALK-positive cancers." (PMID 24509625, 2014). "ALK pathway is one of the most frequently deregulated pathways in various human cancers." (PMID 25193856, 2014). "Authors suggest as this evidence may create the basis for several hypotheses explaining mechanisms by which combinations of KRAS and ALK status might exist through clonal cancer evolution." (PMID 24691006, 2014). "In ALK-expressing cancer cell lines and primary human tumors, transfection with miR-96 decreases levels of the different forms of ALK protein, and decreases the phosphorylation of ALK target proteins, resulting in reduced proliferation, colony formation, and migration." (PMID 24678958, 2014). "In this subset of NSCLC patients who are Chinese male never smokers, EML4-ALK translocation is associated with early-onset and less-differentiated carcinomas, which are likely caused by the aberrant expression of ALK mRNA and protein." (PMID 25407901, 2014).
cancer (continued). "YI has found characteristic pathological features of ALK positive cancer." (PMID 23289484, 2013). "Thus, overexpressed alk is capable of promoting cell proliferation in the nervous system, similar to the situation in ALK-related cancers." (PMID 23667670, 2013). "This makes ALK an intriguing target as a therapy for many other cancers." (PMID 24163262, 2013). "On the basis of the previously reported pathological pattern for ALK-positive carcinomas, 57.14% (4/7, Cases 1, 3, 4 and 5) of ALK-positive cases showed the solid signet-ring cell pattern and 42.86% (3/7, Cases 2, 6 and 7) of cases showed the mucinous cribriform pattern." (PMID 23341890, 2013). "ALK fusion proteins have also been reported in other cancers." (PMID 22852078, 2012). "An analysis of 18 published gene expression data sets from different cancers shows that overexpression of ALK, its smaller homolog LTK (leukocyte tyrosine kinase) and the ligands PTN and MK in cancer tissues from patients correlate significantly with worse course and outcome of the disease." (PMID 23267434, 2012). "Additionally, ALK dysregulation has been found to carry histological and prognostic significance, underscoring the importance of these genetic changes in such cancers." (PMID 22347506, 2012). "The similarity in the location of these ALK mutations, and thus the corresponding LTK mutations investigated in our study, to other activating tyrosine kinase domain mutations in cancer underscores the important consequences of mutation of this region of tyrosine kinases." (PMID 22347506, 2012). "However, cancers characterized by expression of ALK fusions are clinically-sensitive to specific ALK inhibitors." (PMID 20624322, 2010). "In addition to ICIs, future directions in immunotherapy for ALK-positive NSCLC may include the development of ALK-specific cancer vaccines, which could be used in combination with ALK-TKIs or ICIs to enhance antitumor efficacy against ALK-rearranged NSCLC." (PMID 40894217, 2025). "The LLM processes this information and infers that due to this resistance, nalatinib might not be an effective medication for treating cancers caused by the ALK-p.L1196M mutation." (PMID 39775838, 2025). "The first cancer diagnostic product-ExoDX Lung (ALK) was launched by Exosome Diagnostics in 2016, which is an exosome-based technology detecting RNA and ctDNA simultaneously and performing real-time screening for EML4-ALK mutations in patients with non-small cell lung cancer (NSCLC)." (PMID 41220804, 2025). "Furthermore, mutations in cancer therapeutic targets can greatly affect drug sensitivity, and mutation-driven resistance is common in cancer, such as resistance to HER2 and its inhibitors, and resistance to ALK and different generations of ALK inhibitors." (PMID 39981234, 2025). "However, outside of NSCLC, ALK fusions are exceedingly rare, occurring in only ~ 0.2% of cancers." (PMID 40576713, 2025). "This ongoing research into the molecular mechanisms of TPM3‐ALK fusions and their role in cancer pathogenesis continues to provide valuable insights into potential therapeutic strategies and the development of more effective treatments for patients with ALK‐rearranged tumors." (PMID 41275415, 2025). "Notably, strong ppERK increase in drug-treated cells was observed in response to even low levels of light (8 mW/cm2), a level that did not provide measurable increase in untreated cells, suggesting that ALK inhibition can sensitize cancer cells to weak RTK signals." (PMID 39488530, 2024). "This lack of participation may be attributed to the rarity of ALK or ROS1 mutations in these cancers." (PMID 38399413, 2024). "Moreover, inhibiting Src with saracatinib was effective in ALK-resistant cancer cells." (PMID 38397899, 2024).
cancer (continued). "This cohort study of 22 101 patients with NSCLC found that increased targeted therapy use for patients with nonsquamous cancer with EGFR sequence variants or ALK rearrangement in period 2 (2017-2019) was associated with better OS than for similar patients in period 1 (2014-2016)." (PMID 38334998, 2024). "Later on, other gatekeeper mutations, such as ALK‐L1196M, ROS1‐L2026M, FGFR1‐V561F/M, FGFR2‐V564F/I, FGFR3‐V555E, FGFR4‐V550L/E/M, RET‐V804L/M, FLT3‐F691I/L, KIT ‐T670I, and PDGFRα‐T674I, were identified in patients with IGST, NSCLC, or other cancers after corresponding TKI treatment." (PMID 39184861, 2024). "The fact that VH20 targeting TCE and CARs eradicates both cell lines indicates that VH20 targeting ALK seems independent of ALK mutation status, which might be superior to traditional TKIs and can be applicable to a broad population of cancer patients." (PMID 38804307, 2024). "ALK expression was associated with methylation of regions/probes harboring repressive histone marks as indicated by the enrichment of chromatin regulators of the PRC2 complex (EZH2, SUZ12, and JARID2), which has been described as “epigenetic switching” in cancer." (PMID 38585847, 2024). "Our data show ceritinib as an effective treatment of CCA, which could be potentially explored in the other cancer types without ALK mutations." (PMID 38399413, 2024). "This difference may be due to there being limited approved and experimental ALK inhibitors for patients with PD following alectinib treatment versus crizotinib treatment, and due to missing data on subsequent anti-cancer therapy for patients who were lost to follow-up." (PMID 39282663, 2024). "In addition, significant differences in gene expression were observed by RNA-seq analysis when comparing transcriptional profiles of acutely treated cells (48 hours), DTPs, and cells exhibiting acquired resistance across EGFR-mutant and ALK fusion-positive cancer cell lines under therapy." (PMID 38702301, 2024). "Indeed, great multi‐cancer diagnostic value in tissues was observed in small eccDNAs originated from some specific genes, especially the combination of PLD1 and ATF6, or ETV6 and ALK." (PMID 37649244, 2023). "CDKN2A, IKZF1, ETV6, RUNX1, and FLT3 were the top genes mutated in leukemias, while somatic alterations in ALK, NF1, and PTEN primarily occurred in solid tumors, suggesting that the driver alterations are either common to cancer (e.g., cell cycle) or specific to pediatric cancer histotype." (PMID 36845394, 2023). "In cancer, virtually all genomic breakpoints leading to ALK chimeras are located within the intron between exons 19 and 20 (NM_004304.3), leading to the fusion of the intracytoplasmic domain of ALK (exons 20–29) with different partners, which provide dimerization domains." (PMID 36845713, 2023). "Considering that the ERBB family member ERBB3 was reported to recruit PI3Kβ and thereby drive PI3Kα inhibitor resistance in HER2‐amplified and PIK3CA mutant cancers, we hypothesized that ALK inhibition may similarly activate EGFR and thereby regulate PI3Kβ function." (PMID 36423211, 2023). "Except for these targets, the following proteins related to cancer cell proliferation could also be targeted by PROATCs: AR, ALK, BLK, BRD7/9, CDK2/5, CDK8, CDK9, Cdc20, c-Met, CREPT, CYP1B1, DHODH, ER, ERK1/2, FLT-3, HER2, MEK1/2, KRASG12C, GSPT1, PLK1, SLC9A1, TACC3, TRIM24, TRKA/C, Wee1, α1A-AR." (PMID 35410300, 2022). "Indeed, ALK is known to be oncogenic in different types of cancer such as Non-Small Cell Lung Cancer (NSCLC) and it has a critical role in neuroblastoma, both as a consequence of gene translocation, overexpression, point mutations or hyper-phosphorylation of the downstream pathways." (PMID 35351152, 2022). "Indeed, the employment of ALK neutralizing antibody rather than TKI may represent a successful strategy to block the ALKAL2/ALK autocrine loop driving cancer growth in patients that currently have very limited treatment options." (PMID 35351152, 2022).
cancer (continued). "In contrast to the first and second generations of ALK inhibitors, treatment resistance in the case of lorlatinib is not driven by ALK (acquired) point mutations but is instead driven by the pathway evasion strategies of the cancer cells, namely through the PI3K-Akt-mTOR and the RAS/MAPK pathways." (PMID 34575503, 2021). "However, one alectinib-resistant cancer did not feature resistance to ALK, yet, a PIK3CA G106V mutation was found, known to be linked to EGFR inhibitor treatment resistance in EGFR-mutant NSCLC." (PMID 33572278, 2021). "Moreover, upstream of both RAF and PI3′-kinase signaling are the large family of receptor tyrosine kinases, such as EGFR, MET, ROS, ALK, and NTRK, that are mutated in a wide range of different cancers and for which there are numerous FDA-approved drugs linked to predictive biomarkers." (PMID 34298710, 2021). "cfChIP targeting somatic cancer mutations is a promising new methodology for which the basis of liquid biopsies could help understand how expression of mutated oncogenic drivers such as EGFR, ALK, MET and KRAS contribute to carcinogenesis." (PMID 34453867, 2021). "A finely-tuned understanding of cancer biomolecular alterations led to major improvements for patient management as illustrated by the targeting of EGFR (epidermal growth factor receptor) alterations or ALK (anaplastic lymphoma kinase)/ROS1 (ROS proto-oncogene 1) rearrangements in NSCLC." (PMID 34298636, 2021). "Therefore, it is plausible that ALK-altered cancer cells may have the ability to trigger antibody responses in patients." (PMID 32059449, 2020). "Furthermore, to define the best strategy of therapeutic sequence, a better knowledge of the biological and clinical aspects of cancers harboring ALK aberrations is highly recommended, thus offering patients the strongest and longest response with the best quality of life." (PMID 33352844, 2020). "From these data, we sought to determine whether therapeutic monomerization of ALK fusion proteins is a valid anti-cancer strategy for tumors without ALK gain-of-function mutations." (PMID 32300555, 2020). "Therefore, a better understanding of the emerging roles of ALK in human immune responses may provide novel insights for the development of next generation ALK immunotherapies for ALK-altered cancers." (PMID 32059449, 2020). "As, among TKIs, crizotinib somehow targets different proteins, it will be interesting to test in the future whether known inhibitors of c-Met, ALK, and Stat5 have similar sensitizing effects or mechanisms of action against P-gp-overexpressing drug-resistant cancer cells." (PMID 32528877, 2020). "Therefore, it will be interesting to examine if ALK inhibitors could be further explored as potential adjuvants to promote or enhance T-cell based immunotherapies by upregulating HLA expressions in cancer." (PMID 32059449, 2020). "Furthermore, FOXM1 may be a potential therapeutic target in ALK + ALCL, and disruption of the binding between FOXM1 and NPM1 in the NPM-ALK—NPM1 heterodimers may serve as a highly specific anti-cancer therapeutic approach for NPM-ALK + ALCL." (PMID 31390744, 2019). "Subsequent study of molecular markers in cancer cells (ALK, ROS1, EFGR mutations) were negative." (PMID 30986912, 2019). "We recently addressed this topic too by evaluating the frequency of an extended panel of cancer-relevant mutations that could have possibly affected the initial response to erlotinib in a consecutive series of EGFRM+/ALK-negative/ROS1-negative advanced NSCLCs." (PMID 31266248, 2019). "NPM1 is not the only ALK fusion partner that has been associated with cancer." (PMID 31366041, 2019).
cancer (continued). "Of note, in mice crizotinib could be safely administered without any obvious toxicity to reach a concentration of 10 μM in plasma, lung tissues and tumors, which is the dose that is effectively inducing ICD hallmarks in cancer cells that lack ALK rearrangements." (PMID 30940805, 2019). "Thus, AXL associated with the development of EMT may be a promising therapeutic target for the elimination of cancer in ALK-positive NSCLC cells." (PMID 29930762, 2018). "Given the importance of ALK in pathogenesis of neural crest-derived cancers, we considered the possibility that phosphorylation of these tyrosines might be an important mechanism for ALK-dependent tuning of GSK3 activity, which should be specific to the neural crest lineage." (PMID 29555900, 2018). "This approach could be effective not only in RAS-mutant-driven cancers but also those driven by mutations in EGFR, and, by extension, possibly in tumors driven by other upstream receptor tyrosine kinases, such as MET and ALK." (PMID 30590030, 2018). "Several second-generation ALK-TKIs may become first-line therapies of this cancer in future." (PMID 30400214, 2018). "However, cancer cells with EGFR T790M and ALK L1196M mutations acquire drug resistance." (PMID 29721209, 2018). "Our retrospective analysis of ALK-rearranged Sq-LC revealed that ALK-rearranged Sq-LC may occur as a result of unexpected biological events and independent of ALK rearrangement due to the heterogeneity of the cancer." (PMID 29844868, 2018). "Furthermore, SRC inhibition by AZD0530 was effective in ALK‐resistant cancer cells." (PMID 28396832, 2017). "Therefore, it’s important to identify the ALK gene status to promote personalized cancer therapy." (PMID 29088875, 2017). "Similarly, we propose that treatment with stemness-targeting agent rapamycin could sensitize EML4-ALK+ NSCLC cells to conventional cancer drugs including ALK inhibitors." (PMID 26517679, 2015). "Therefore, in future, the development of drugs that stop FAM150A and FAM150B from binding to ALK may be useful for treating cancers that are driven by high levels of ALK activity." (PMID 26418745, 2015). "The success of various tyrosine kinase inhibitors in the treatment of different cancers as well as the increased number of human malignancies involving aberrant ALK activity, both in children and adults, encouraged the search and motivated the development of ALK-selective small-molecule inhibitors." (PMID 26299615, 2015). "Indeed, cancer cells where genomic alterations of ALK lead to expression of truncated variants, such as NSCLC (EML4-ALK) and ALCL (NPM-ALK), are addicted to ALK signalling because translocations provide dimerization domains that render fusion proteins ligand independent." (PMID 26147305, 2015). "Furthermore, since ALK expression in normal adult tissues is found in very low levels, selective ALK inhibitors would exhibit sufficiently wide therapeutic windows in patients with ALK-activated cancers." (PMID 26299615, 2015). "Importantly, ALKF1174L may secondarily arise as a mechanism of resistance after an initial response to crizotinib in patients with ALK-rearranged cancers." (PMID 26299615, 2015). "Finally, it is worth stressing the low-affinity interaction identified between rucaparib and ALK (IC50 = 18 μM), which might partially explain the increased efficacy of rucaparib in cancer cells with alterations in ALK." (PMID 24632590, 2014). "The first group consists of cancer cells whose drug resistance can be overcome by exposing the cells to GCs in combination with drugs that target protein kinases such as Akt, mTOR, Src, ALK, and/or BCR, or drugs antagonizing Bcl-2, Bcl-XL, Mcl-1, c-Myc, or Notch." (PMID 23431463, 2013). "Moreover, GTx-186 effectively inhibited ALK phosphorylation and ALK-dependent cancer cell growth." (PMID 24386191, 2013).